RB1 (RB transcriptional corepressor 1)
Diseases named in the same sentence as RB1 in open-access papers (continued):
Sharing a sentence is not in itself a finding about the gene and the disease.
breast cancer (continued). "We show this for the BRCA2 gene, which like RB1 is one of most commonly affected cancer predisposition genes in the affected pediatric population, and in some populations has been shown to have a parent-of-origin effect with paternal origin of mutation affecting breast cancer penetrance." (PMID 39724000, 2024). "Notably, among those genetic alteration events whose loss enhances CDK4/6i sensitivity, CDK6, CCND3, CCNE1 and E2F3 were frequently amplified in the genomes of breast cancer patients, whereas among the genes whose loss promotes resistance, RB1, REXO2, PPP2R2A and STT3A were mainly depleted." (PMID 34508104, 2021). "Moreover, the acquisition of multiple de novo somatic Rb1 mutations in metastatic breast cancer patients may result in the emergence of a resistance to CDK 4/6 inhibitors." (PMID 31058077, 2019). "We hypothesized that inhibition of CDK4/6 would protect normal cells with an intact G1 restriction checkpoint (Rb1 competent) from Mps1 inhibitor-associated toxicities while remaining cytotoxic to tumor cells, such as basal-a breast cancer, which have lost the checkpoint." (PMID 26398286, 2015). "Similar to MYC gain, RB1/INTS6 loss could be evolutionarily conserved in mammary tumor development." (PMID 20735817, 2010). "Germline mutations affecting the RB1 gene are strongly associated with retinoblastoma development in children, and recent evidence has revealed an increased risk of different malignancies, including breast cancers, among patients cured from hereditary retinoblastoma." (PMID 20594292, 2010). "RBness breast cancers frequently exhibited cyclin E1 (CCNE1) amplifications compared to RB1-defective breast cancers." (PMID 40138429, 2025). "We demonstrated that RB1 knockdown in abemaciclib-treated breast cancer cells resulted in reduced lysosomal biogenesis, accompanied by decreased sensitivity to lysosomotropic agent-induced cell death triggered by abemaciclib." (PMID 39930269, 2025). "This was achieved through the direct modification of histone acetylation on the Rb1 promoter, resulting in the silencing of RB1 expression in diverse mouse models like 4T1 mammary carcinoma, Lewis lung carcinoma, and EL-4 thymoma." (PMID 39858465, 2025). "This prospective study aimed to provide a comprehensive analysis of the methylation status of two pivotal genes, CDKN2A/p16INK4A (cyclin-dependent kinase inhibitor 2A) and RB1 (retinoblastoma transcriptional corepressor 1), in breast cancer patients." (PMID 38716944, 2024). "RB transcriptional corepressor 1 (RB1) fostered the development of breast cancer by PI3K/AKT signaling." (PMID 38654239, 2024). "This study investigated the methylation statuses of CDKN2A/p16INK4A and RB1 genes in breast cancer patients." (PMID 38716944, 2024). "This extends to RB1 epigenomics, as methylation patterns in RB1 have been suggested to predict the recurrence of malignant breast tumours." (PMID 39595122, 2024). "Outside activation of the MAPK pathway, RB1 loss and FAT1 loss were recently reported to contribute to CDK4i/6i resistance in ER+ breast cancers." (PMID 38066089, 2024). "Through a genome-wide CRISPR screen, we identify protein arginine methyltransferase 5 (PRMT5) as a molecular vulnerability in ER+/RB1-knockout breast cancer cells." (PMID 38480701, 2024). "Depletion of RB1 in breast cancer and osteosarcoma cells results in sensitivity to DNA-damaging drugs, a sensitivity further exacerbated by the PARP inhibitor Olaparib." (PMID 38672640, 2024).
breast cancer (continued). "Here, the authors identify a vulnerability of ER + /RB1- breast cancer on PRMT5 and via dual blockade of ER and PRMT5 therapeutically target this in patient-derived xenograft models." (PMID 38480701, 2024). "It is worth noting that ACSL4 is upregulated in therapy-resistant prostate and breast cancer, in which RB1 inactivation most commonly occurs." (PMID 36928314, 2023). "Recent studies in mouse breast cancer models showed that FoxM1 binds directly to the RB1 protein and forms repressive transcriptional complexes, which suppress the Pten tumor suppressor gene and are essential for tumor cell plasticity and metastasis." (PMID 37686402, 2023). "To mimic RB1 loss-of-function alterations, we used CRISPR-Cas9 to delete RB1 in CDK4/6i sensitive MCF-7 and T47D breast cancer cells." (PMID 37502925, 2023). "Using a genome-wide CRISPR screen, we identified protein arginine methyltransferase 5 (PRMT5) as a molecular vulnerability in ER+/RB1-knockout (RBKO) breast cancer cells." (PMID 37502925, 2023). "In breast cancer, downregulation of c-Myc can promote senescence in breast cancer cells by activating Rb1/p21, while in liver cancer, c-Myc can induce senescence in hepatocellular carcinoma cells by regulating telomerase activity." (PMID 37433010, 2023). "We found that RB1-mutant breast cancer cell lines were significantly sensitive to rucaparib and olaparib in the GDSC data set." (PMID 37937640, 2023). "On the one hand, breast cancers evolved resistance mechanisms, such as RB1 inactivation or ESR1 gain-of-function changes, to deregulate cell cycle control and drive aggressive cell growth and proliferation." (PMID 37475004, 2023). "Correlation analyses also supported that LPAR6 and RB1 shared similar expression patterns both in healthy breast tissues and breast cancer tissues." (PMID 34510318, 2022). "When analyzing breast cancer tumors, including IDCs and ILCs, we observed new mutations in CDKN2A, RB1, CCND2, and CCND3 in the brain metastases of four IDCs, but not in their primary tumor counterparts." (PMID 36507516, 2022). "When compared with ER+ breast cancers, loss-of-function mutations in the retinoblastoma tumor suppressor RB1 (RB) are more common in TNBC (7% versus <4%), and RB pathway alterations have been reported in up to 30% of TNBC." (PMID 34932500, 2022). "A PIP5K1 inhibitor, UNC3230, which has been identified as a chronic pain inhibitor, exhibited exceptional RB1-selectivity in breast cancer cells." (PMID 33591981, 2021). "As a proof-of-concept, focused follow-up studies silencing either RB1 or CDK6 led to significant alteration of drug sensitivity of MCF7 breast cancer cells to CDK4/6i, supporting the reliability of our in vitro screening results." (PMID 34508104, 2021).
breast cancer (continued). "Similar to UNC3230, TAK-243 exhibited exceptional selectivity in RB1 mutant breast cancer and osteosarcoma cell lines, including a dramatic effect at nanomolar concentration range." (PMID 33591981, 2021). "The trial stemmed from promising preclinical results and tested the possibility to enhance treatment efficacy by using intermittent, alternating dosing with palbociclib and paclitaxel, in 27 metastatic Rb1-proficient breast cancer patients." (PMID 34204543, 2021). "We also explored possible relationships between GLUT1–4 and RB1 expression in breast cancer tissues." (PMID 34525987, 2021). "Our models also showed good results on predicting mutations of RB1 (AUC 0.852), CDH1 (AUC 0.776), NF1 (AUC 0.768), NOTCH2 (AUC 0.740) in breast cancer." (PMID 34556802, 2021). "Remarkably, employment of D 4476 potentiates the efficacy of ribociclib in inhibiting RB1 phosphorylation in multiple CDK4/6i resistant breast cancer cells, accompanied with antagonizing CDK4/6i treatment induced CDK6 protein accumulation." (PMID 34508104, 2021). "Accordingly, the blockade of IL-6 by neutralizing antibody suppressed breast cancer progression is induced following RB1 inactivation." (PMID 34359636, 2021). "In support of the critical roles they played in cell cycle progression, loss of RB1 and upregulation of CDK6 rank on the top hits in driving breast cancer cell evasion from CDK4/6i treatment induced cell cycle blockade." (PMID 34508104, 2021). "Mechanistically, cyclin E-CDK2 and cyclin D1-CDK4/6 complexes can suppress Smad3 through its phosphorylation, and the suppression of Smad3 releases the Rb1-E2F blockade and restore cell cycle arrest in breast cancer cells." (PMID 34123801, 2021). "Here, we used GEPIA and LinkedOmics databases to investigate the prognostic value of SLC2A1–4 and RB1 gene expression in breast cancer." (PMID 34525987, 2021). "Intriguingly, the expression of cdk4, cdk6, e2f1, and rb1 in breast cancer was moderate or low compared to that in all tumors." (PMID 32357912, 2020). "Of note, deletions at 13q (BRCA2 and RB1) commonly identified in breast cancer were discovered in 3/5 (60%) CTC samples." (PMID 32650480, 2020). "Analysis of breast cancer patients revealed heterogeneous RB1 expression at both mRNA and protein levels in basal tumors." (PMID 32826891, 2020). "It is known that FNDC3B is highly amplified in esophageal, lung, ovarian, and breast cancer and it has been associated with the activation of several cancer pathways including PI3-kinase/Akt, Rb1, and TGF-β signaling." (PMID 31093274, 2019). "Instead of directing flows with cell cycle regulators as in the case of breast cancer, there are in general uncoordinated functions between RB1 with transcriptional regulators LMO2 and PML and RFC1 that regulate DNA replication." (PMID 26975659, 2016).
breast cancer (continued). "Key transcriptional regulators that had been implicated in breast cancer pathogenesis such as RB1, FOXM1 and E2F1 are key targets within our model and the high values of flow differences further highlight their importance in breast cancer." (PMID 26975659, 2016). "Through in vitro experiments, they revealed the same strengths and weaknesses of this drug as was found in breast cancer: PD0332991 inhibited cell proliferation in Rb1 proficient glioblastoma cells and Rb1 deficiency caused resistance." (PMID 26649278, 2015). "In breast cancer, the RB1 pathway is believed to be inactivated via several mutually exclusive mechanisms." (PMID 23401782, 2013). "Next, we analyzed the effect of RB1 status on selected anti-neoplastic drugs used to treat different types and grades of breast cancer." (PMID 24265703, 2013). "Deletion of Rb1 in mouse mammary stem/bipotent progenitor cells induced focal acinar hyperplasia with squamous metaplasia that progressed in transplantable mammary tumors similar to either luminal-B or TNT subtypes." (PMID 23900261, 2013). "We performed a retrospective analysis of CtIP/RBBP8 and RB1 levels by immunohistochemistry using 384 paraffin-embedded breast cancer biopsies obtained during tumor removal surgery." (PMID 24403251, 2013). "For instance, STAG1 is a cell cycle regulator and its overexpression is reported for breast cancer and cellular proliferation, while the methylation of RB1 by SMYD2 enhances cell cycle progression." (PMID 23922792, 2013). "Loss of RB1 function is associated with a variety of human cancers, while inactivation of the RB1 tumor suppressor gene has been reported in several human malignancies in addition to RB, such as cancers of the breast, prostate, and lung." (PMID 23233783, 2012). "In the current study, we analyzed 73 breast cancers undergoing pre-surgical treatment with doxorubicin or mitomycin with 5-FU for genetic and epigenetic changes in the RB1 gene." (PMID 20594292, 2010). "In this study, we evaluated potential point mutations through gene sequencing (N = 73) and intragenetic deletions by use of MLPA (N = 71) across the whole coding region of the RB1 gene in stage III breast cancers." (PMID 20594292, 2010). "RB1-inducible coiled-coil 1 (RB1CC1) plays a significant role in the enhancement of the retinoblastoma tumor suppressor (RB1) pathway and is involved in breast cancer development." (PMID 21203526, 2010). "While the cellular functions of pRb are well characterized, the effect of disturbances in the RB1 gene on tumor growth and response to systemic therapy in breast cancer is incompletely understood." (PMID 20594292, 2010).
breast cancer (continued). "Previous studies have reported allelic imbalance (AI), loss of pRb protein expression, hypermethylation of the RB1 promoter and, in some rare cases, large intragenic deletions in the RB1 gene in primary breast cancer." (PMID 20594292, 2010). "The coordinated expressions of RB1, p16 and p21 influence the proliferation activity in clinical breast cancer." (PMID 21203526, 2010). "This is consistent with the frequency of RB1 LOH seen in previous studies of breast cancer (26 to 47%)." (PMID 18782450, 2008). "The inverse relationship between p16INK4a and RB1 expression in breast cancers has been previously reported; however, this relationship and its association with basal-like tumours is new in this report." (PMID 18782450, 2008). "There are a few reports of alterations in RB1 in breast cancer with two reports showing structural changes as assessed by Southern blotting in 7% and 19% of primary tumours, and no published reports to our knowledge of point mutations." (PMID 18782450, 2008). "Due to the low expression of RB1 message in basal-like tumours we decided to examine these breast carcinomas for LOH at the RB1 locus." (PMID 18782450, 2008). "We also simulated PAC detection of recurrent mutations with two breast cancer cell lines, of which HCC1937 had skipped RB1 exon 22, and we were already able to identify the mutant from among two samples up to even five mutants from among six samples." (PMID 18688287, 2007). "For example several tumor suppressor genes known to play a role in breast cancer, such as RB1, PTEN and BRCA2, were frequently lost, but rarely gained, in our data set." (PMID 16457699, 2005). "However, within breast cancer subtypes, basal‐like breast cancer exhibited substantially lower RB1 mRNA and protein levels compared to other subtypes." (PMID 40070134, 2025). "Similarly, we report RB1 somatic abberations in 3/34 (~ 8.8%) cases exclusively in the post treatment setting in line with that reported in the literature in CDKI resistance breast cancer." (PMID 41372771, 2025). "Whole-genome sequencing of breast cancer models and paired primary-metastatic samples demonstrated that active APOBEC3 mutagenesis promoted therapy resistance through characteristic alterations such as RB1 loss." (PMID 40379787, 2025). "The peptides upregulate suppressors NR3C1, BRCA1, BRCA2, SFN, and RB1, which may initiate apoptosis processes and growth regulation in breast cancer cells, potentially preventing tumor progression." (PMID 40043049, 2025). "In the PALOMA 3 trial, 4.7% of patients developed on-treatment RB1 mutations, indicating that CDK4/6 inhibitor therapy may provide selective pressure, leading to the development of Rb loss in a subset of breast cancer patients." (PMID 40075623, 2025). "Another widely recognized suppressor gene RB1 and is often missing in basal-like breast carcinomas." (PMID 40043049, 2025). "Our data may also be applicable to MYCN signaling pathways in other cancers in which RB1 inactivation occurs, including lung, ovarian and breast cancers." (PMID 39079981, 2024). "Consequently, inhibiting CDK4/CDK6 can enhance the tumor-suppressive function of RB1, as demonstrated in breast cancer treatment." (PMID 39664374, 2024). "Notably, cell cycle regulatory proteins including CD4/6 and RB1 have been found to have a significant impact on the regulation of breast cancer cell proliferation." (PMID 37885035, 2023). "The nanoparticle carriers of Rb1 and Rb1 all showed cytotoxicity to breast cancer cells in vitro, although it remains unclear how they induce apoptosis." (PMID 37749560, 2023).